VHL (von Hippel-Lindau tumor suppressor)
Diseases named in the same sentence as VHL in open-access papers (continued):
Sharing a sentence is not in itself a finding about the gene and the disease.
tumor (continued). "Given the multiple functions of pVHL the inactivation of VHL is a critical point in the initiation of tumor formation in the context of ccRCC." (PMID 27530247, 2016). "Von Hippel Lindau (VHL) is a tumour suppressor that is lost in the majority of clear cell RCC (ccRCC) cases." (PMID 27358011, 2016). "mTOR phosphorylation was detected in all the three SDHB-related PPGLs, while it was detected only in one VHL-related tumor." (PMID 27990160, 2016). "H&E confirmed comparable primary tumour sizes but increased lung metastasis, VHL knockout in primary tumours and increased metastatic burden in the lungs." (PMID 27358011, 2016). "Collectively, our in vitro and in vivo studies reveal for the first time that wogonin represses MM-stimulated angiogenesis and tumor progression via c-Myc/VHL/HIF-1α signaling axis." (PMID 26735336, 2016). "We confirm that VHL tumours from the same patient are independent but that the combination of genetic and environmental background significantly influences both sCNVs and the types of sSNVs acquired." (PMID 27174753, 2016). "Taken together, these observations strongly indicate that in addition to VHL-inactivation, there is a requirement for additional genetic alterations to provoke ccRCC tumor development." (PMID 27491826, 2016). "Characterizing the differences in tumour progression between RENCA VHL null cells and RENCA control cells should be the focus of future studies." (PMID 27358011, 2016). "A considerable amount of evidence shows that HIF1α plays a tumor-suppressive role in VHL-defective renal carcinogenesis." (PMID 26743088, 2016). "It is therefore possible that in VHL patients, VHL inactivation occurs in components of the tumor microenvironment in addition to the tumor itself." (PMID 27733136, 2016). "In fact, in addition to this CYLD tumor suppressor, several key tumor suppressors and oncogenes such as the VHL, PDGFR-α, and Shh/Patched 1 (Shh/Ptch1) were recently identified to regulate ciliogenesis." (PMID 31093340, 2016). "The VHL gene is a tumor suppressor gene of 639 coding nucleotides distributed over three exons and located at chromosome 3p25.3." (PMID 27530247, 2016). "Combined with our findings, this suggests that VHL loss creates an environment where HIF-1α expression drives tumour metastasis and HIF-2α promotes tumour growth." (PMID 27358011, 2016). "Another interesting cell line is RCC4, a vhl mutant derived from a primary tumor widely used as a model for VHL-dependant mechanisms, witha commercially available counterpart cell line with restored wild-type gene." (PMID 27993170, 2016). "The evidence of biallelic inactivation of VHL found in tumor samples is consistent with Knudson's “two-hit model” where a mutation in one of the alleles is inherited, and the wild-type allele is somatically inactivated leading to tumorigenesis." (PMID 27069690, 2016). "VHL is a known tumor suppressor, which targets HIFs for degradation with its E3 ubiquitin ligase activity." (PMID 27542736, 2016). "The von Hippel-Lindau (VHL) is a putative tumor suppressor gene which has been proposed to exert inhibitory effects on angiogenesis and tumor cell migration, through negative regulation of HIF1 and the stromal-derived factor-1 (SDF-1) receptor, CXCR4." (PMID 27540529, 2016). "Increased blood vessel formation can already be observed surrounding microscopic VHL mutant ccRCC precursor lesions in kidneys of VHL patients, showing that the induction of neoangiogenesis occurs at the earliest stage of tumor development." (PMID 27528422, 2016). "Other tumor suppressor gene VHL, Von Hippel–Lindau tumor suppressor also inhibits IGF1R promoter activity through interaction with Sp1 protein." (PMID 27405474, 2016).
tumor (continued). "In tumor BC_2R, focal SCNAs were present in regions covering VHL, SEDT2, PBRM1 and BAP1, while focal SCNAs were only detected in the region covering VHL in the left tumor (BC_2L)." (PMID 27383411, 2016). "In contrast, the UA or CAY10585–treated cells markedly enhanced in VHL (tumor suppressor) levels compared with the AdRHIF-1α group." (PMID 27708244, 2016). "In patient BC_2, a deleterious frameshift deletion in VHL was present in tumor BC_2R, while CpG sites with high methylation level were detected in the VHL promoter in tumor BC_2L." (PMID 27383411, 2016). "The group differences in DNA and/or histone methylation suggested in this previous study were supported by our data, which showed increased H3K4me3 and H3K9me3 levels in VHL mutant PCC tumor cells compared to non- VHL mutant PCC." (PMID 26472283, 2015). "Central to the adaptive mechanism of the hypoxia response pathway is the tumor suppressor, E3 ligase, Von Hippel-Lindau protein (VHL), which plays a key part in cellular oxygen sensing by targeting hypoxia-inducible factors (HIF) for proteosomal degradation." (PMID 26561808, 2015). "The von Hippel-Lindau (VHL) gene on chromosome 3 (3p25–26) has been identified as a tumor suppressor gene for this syndrome." (PMID 26500709, 2015). "Upon deletion of VHL in tumor-specific CD8+ T cells, hypoxia modulates expression of effector molecules through HIF-1α and 2α to enhance function and control of persistent viral infection and tumor growth." (PMID 26393659, 2015). "The human von Hippel-Lindau (VHL) tumor suppressor is a marginally stable protein previously used as a model substrate of eukaryotic refolding and degradation pathways." (PMID 26027734, 2015). "The somatic inactivation of the normal allele in PCC/PGL tumour suppressors such as SDHx, VHL and NF1 tumours is driven by large deletions at the corresponding loci, but not by somatic mutations or epigenetic modifications." (PMID 25625332, 2015). "The tumor suppressor VHL is an E3 ubiquitin ligase responsible for regulating the degradation of hypoxia-inducible factor 1α (HIF-1α)." (PMID 26474388, 2015). "In contrast, several other studies revealed favourable prognosis for tumours with VHL inactivation or alteration." (PMID 26448938, 2015). "Instead of analyzing tumor tissues, we analyzed normal-appearing tissues of VHL patients in which tumors are known to frequently occur, spinal cord and cerebellum." (PMID 28326266, 2015). "JARID1C is proposed to have a tumor suppressor role - its knockdown in 786-O VHL-/- ccRCC cells significantly enhanced tumor growth in a mice xenograft model." (PMID 28326264, 2015). "The VHL tumor suppressor gene codes for VHL protein that regulates cellular response to hypoxia by targeting hypoxia-inducible factor." (PMID 28326273, 2015). "VHL tumours (Cluster C1B) were characterized by a combined deletion of chromosome 3 (harbouring VHL) and arm 11p." (PMID 25625332, 2015). "Positive feedback loop between VEGF and miR-155 exists, and miR-155 decreases the expression of VHL tumor suppressor, a protein with ubiquitin ligase activity sequestrating, for example, hypoxia-induced factors (HIFs)." (PMID 26064968, 2015). "The loss of heterozygosity (LOH) of 3p loci, including FHIT, VHL, and RASSF1A (known tumor suppressors), has been confirmed in ESCC, and loss of FHIT has been reported to be associated with poor prognoses." (PMID 26465158, 2015). "The study of tumor-free central and peripheral nervous system tissue of VHL patients revealed numerous microscopic structures that are not encountered in similar tissues of non-VHL control patients." (PMID 28326266, 2015).
tumor (continued). "Tumour metabolites have also been shown to correlate with tumour-specific genetic mutations, for example, IDH1 mutation in glioma, SDH and VHL mutations in paraganglioma and MYCN amplification in neuroblastoma." (PMID 26348444, 2015). "pVHL, as the product of Von Hippel-Lindau (VHL) tumor suppressor gene, functions as the substrate recognition component of an E3-ubiquitin ligase complex marking specific target proteins for degradation." (PMID 26309161, 2015). "It was shown that miR-155 targets several tumor suppressors such as SOCS1, FOXO3, and VHL and is involved in the regulation of cell survival, growth, chemosensitivity and tumor angiogenesis." (PMID 26156018, 2015). "In accordance with the results of our study, the restoration of COL6A1, which is expressed at low levels in the VHL−/− cell line 7860, promoted tumor growth." (PMID 26317545, 2015). "Loss of VHL function upregulates HIF-1α, a transcription factor that leads to an overexpression of VEGF and drives tumor angiogenesis." (PMID 26021863, 2015). "In another example, MD simulation has deciphered the dynamic interaction between two tumor-related molecules, VHL and hypoxia-inducible transcription factor 1α (HIF1α) where distant two VHL regions are involved in its binding to HIF1α." (PMID 25781978, 2015). "The VHL tumor suppressor gene had been cloned, and enormous progress were made toward the understanding of the molecular biology and biological function." (PMID 25091575, 2014). "The summary statistics for the VHL molecular markers were produced for each objective tumor response category." (PMID 25100134, 2014). "Collectively accumulating evidence clearly demonstrates VHL being a critical tumor suppressor of ccRCC." (PMID 25277181, 2014). "VHL protein is widely expressed in human tissues and its best documented tumor suppressor function is the negative regulation of hypoxia-inducible target genes involved in angiogenesis, erythropoiesis and energy metabolism." (PMID 25490036, 2014). "The current findings agree with Knudson’s two-hit theory that, in addition to gene mutation and hypermethylation, LOH is one of the major mechanisms resulting in tumor suppressor gene (such as VHL gene) inactivation." (PMID 25217002, 2014). "The VHL tumor suppressor is an E3-ubiquitin ligase recognizing regulatory proteins such as the alpha subunits of the Hypoxia Inducible Factors (HIFs), the interaction being followed, generally, by ubiquitination and proteasomal degradation of the partner." (PMID 24657971, 2014). "MBD1 has been shown to bind the promoters of known tumor suppressor genes (e.g. p16, VHL and E-cadherin)." (PMID 24362839, 2014). "In two patients with ccRCC tumors arising from germline VHL mutation, ITH was minimal despite extensive sampling in both a morphologically heterogeneous stage 3 tumor and a morphologically homogeneous stage 1 tumor." (PMID 25159823, 2014). "Cul2 is part of the VHL tumor suppression complex that ubiquitinates HIF1α; the disruption of HIF1α has been found to improve the insulin sensitivity and decrease adiposity in mice." (PMID 24628878, 2014). "Intriguingly, VHL itself regulates the expression of miR-155 in ccRCC, suggesting a tumor suppressor-oncogene feedback regulation between VHL and miR-155." (PMID 24849932, 2014). "VHL expression was determined in our cohort of PTC tumor samples (n = 264) by real-time quantitative PCR." (PMID 25490036, 2014). "Tumors form when there is biallelic VHL tumor suppressor gene inactivation in a two hit model of tumorigenesis." (PMID 25217002, 2014). "The results of this study can also be used to establish genetic diversity panels for the VHL tumor suppressor gene in the local population." (PMID 25217002, 2014). "Tumor-specific methylation of the VHL gene is an expected event and was observed in a single probe, but with a frequency slightly below the expected levels of hypermethylation." (PMID 24454902, 2014).
tumor (continued). "Of note, marked variations of PTHLH expression signals, from very high to almost undetectable levels, were observed even in the VHL alteration-positive tumor group." (PMID 24861371, 2014). "VHL silencing leads to dysregulated hypoxia-induced factors and activation of downstream pathways important for tumor progression." (PMID 24423208, 2014). "VHL protein (pVHL) acts as a tumor suppressor through its role as the substrate recognition protein in the E3 ubiquitin ligase complex, VBC." (PMID 24879016, 2014). "The inactivation of VHL is found in 50–80% of clear cell RCCs and is considered to be an essential, first-step molecular alteration in the tumorigenic pathway for this tumor subtype 25,30,31." (PMID 24861371, 2014). "The VHL tumor suppressor gene is located on the short arm of chromosome 3 mapped to 3p25-3p26 and consists of 639 nucleotides in 3 exons encoding 213 amino acids." (PMID 25217002, 2014). "eEF1A has been shown to bind to and promote nuclear export of the von Hippel-Lindau (VHL) tumor suppressor and the polyA-binding protein 1 (PABP1)." (PMID 23799104, 2013). "Gene-specific hypermethylation was first described for the RB gene in retinoblastoma and many other tumour suppressor genes have been reported as methylated in tumours, for example p16, VHL, MLH1, APC and E-cadherin." (PMID 22771539, 2013). "The tumor expression levels of VHL, the endothelial marker CD31, PDGFRα, VEGF and the inhibitor of apoptosis survivin (SVV) are supposed to be important markers for prognosis and outcome of patients with advanced RCC." (PMID 24086736, 2013). "The VHL gene was identified in 1993 and is a tumor suppressor gene; somatic inactivation of the wild-type allele or loss of heterozygosity (LOH) of the VHL gene is often observed prior to development of VHL-associated lesions." (PMID 23384121, 2013). "In tumour tissues, the expression of both VHL isoforms was very variable and depended on the VHL status." (PMID 23785518, 2013). "The cells depleted of VEGF generated much smaller tumors than the control cells in the same mice, suggesting that HIF-induced VEGF expression contributed positively to the tumor growth by VHL-/- cancer cells." (PMID 24260413, 2013). "We show that the Aurora-A transcript and protein levels in ccRCC were correlated with the tumour grade and VHL status." (PMID 23785518, 2013). "The nature of the direct molecular mechanism by which VHL induces FLCN renal tumor suppressors remains to be determined, but is likely to involve multiple mechanisms." (PMID 23922894, 2013). "The form of β-dystroglycan seen in tumour tissue was found to co-migrate with that in UMRC2− cells but the form in normal renal tissue migrated more slowly than that in UMRC2+VHL cells, thus the overall difference was smaller in magnitude." (PMID 23970118, 2013). "We show that FLCN contributes to VHL-mediated suppression of tumor growth by affecting LC3B and LC3C autophagic pathways." (PMID 23922894, 2013). "We then compared the tumor growth of VHL-/- 786-O cells expressing a control shRNA (SCR) with that of the same cells expressing VEGF-1137." (PMID 24260413, 2013). "Because we demonstrated that both LC3B and LC3C exercise important and opposite effects on growth of ccRCC tumors, we propose that the contribution of FLCN to the tumor-suppressing activity of VHL results, at least partially, from its effects on autophagy." (PMID 23922894, 2013). "Abrogation of tumour suppressor function of the Von Hippel-Lindau (VHL) gene is a common feature of clear cell RCC, whereas the driving mutations behind non-clear cell RCC carcinogenesis are less well understood." (PMID 23688003, 2013). "SDHx-related tumors were characterized by an increase in succinate levels in comparison to other tumor subtypes (p = 0.0001 vs VHL and p = 0.000003 vs apparently sporadic)." (PMID 24312232, 2013).
tumor (continued). "Limited prior publications have evaluated tumor vascularity in RCC specimens and the association with VHL mutational status and prognosis." (PMID 23316728, 2013). "Recently, we reported that Src is able to trigger the degradation of the von Hippel-Lindau (VHL) tumor suppressor through direct phosphorylation of VHL." (PMID 23585863, 2013). "The purpose of this work was to determine if FLCN contributes to the tumor suppressing activity of VHL." (PMID 23922894, 2013). "The Aurora-A transcript levels were significantly higher in Fuhrman grade 3 and 4 than in grade 1 and 2 tumours (p=0.0034) and in VHLwt/wt than in VHL mut/del ccRCC samples (p=0.037)." (PMID 23785518, 2013). "VHL is a classical tumour suppressor gene and somatic inactivation of the second copy by LOH, methylation or mutation is observed in tumours from VHL patients." (PMID 22825683, 2012). "Although the expression of both HIF1α and HIF2α is similarly regulated by VHL, their roles in tumor development, tumor metabolism, and response to therapy are sometimes contrasted." (PMID 23178531, 2012). "More than one tumor in the brain or eye, or a single tumor in the brain or eye plus one elsewhere in the body, such as in the pancreas, kidney, liver, or adrenal gland are chraracteristic to diagnose VHL." (PMID 22873581, 2012). "This gene was named as the ‘VHL tumor suppressor gene’, and its location was demonstrated to be on the chromosome 3p25–26." (PMID 23843833, 2012). "Despite their similarities in presenting with pseudo-hypoxic/glycolytic phenotypes, tumor aggressiveness in SDHx- and VHL-derived PHEOs/PGLs is distinct." (PMID 22859959, 2012). "Earlier reports have proposed that the tumor-suppressor function of the VHL protein reflects the role of VHL as an ubiquitin ligase of the transcription factor HIF-1α, which is known as a master regulator of hypoxic response." (PMID 22390300, 2012). "The retinoblastoma (Rb) gene and the von Hippel-Lindau (vHL) gene both downregulate VEGF expression; their mutation leads to VEGF production, angiogenesis, and tumor growth." (PMID 21977033, 2012). "Among the DNA mismatch repair gene MLH1 (3p21.3-p23) and the DNA repair gene XPC (3p25.23), which is frequently found mutated in Xeroderma pigmentosum syndrome type C, this locus contains the VHL (von Hippel-Lindau) tumor suppressor gene." (PMID 23127113, 2012). "The study of VHL-derived tumors initially led to the discovery of pseudo-hypoxia and its supporting role in tumor growth." (PMID 22859959, 2012). "The first is the A498 cell line, which is a VHL tumor suppressor gene mutant and in which hypoxia-inducible factor (HIF)-2α is activated, although HIF-1α is absent." (PMID 22965141, 2012). "Nevertheless, their tumor aggressiveness is distinct: PHEOs/PGLs metastasize rarely in VHL-, but frequently in SDHB-patients." (PMID 22859959, 2012). "The tumor-suppressive function of VHL is best viewed in the context of its role as an E3 ubiquitin ligase that targets various substrates, including HIF-1α and atypical PKC." (PMID 22390300, 2012). "VHL inactivation, either through sequence alterations or promoter methylation in tumor DNA, was observed among 86.6% of ccRCC cases." (PMID 22022277, 2011). "Stable suppression of EGFR by shRNA prevents serum-free growth of VHL-defective ccRCC cells in vitro, and retards the tumor growth of these cells for extended periods in xenograft models, without affecting HIF2αfunctions." (PMID 21949687, 2011). "And the mean tumor volume was obviously decreased 30% by using FA-PEAs to transfer VHL plasmids to treat mice RCC models." (PMID 21513541, 2011). "Restoration of VHL expression in VHL-null 786-O renal cells also results in reduced tumor growth in nude mice." (PMID 21386990, 2011). "In order to validate the expression of target gene delivered by FA-PEAs in the tumor tissues, VHL was detected by RT-PCR and immunohistochemistry." (PMID 21513541, 2011).